PRSS33 (serine protease 33)
Description:
Serine protease that has amidolytic activity, cleaving its substrates before Arg residues.
Synonyms: EOS
Tractability: Antibody: UniProt places it where antibodies can reach, with medium confidence; UniProt predicts a signal peptide or a membrane-spanning region; its Gene Ontology location is reachable by antibodies, with medium confidence.
Gene: Protein-coding gene on chromosome 16 (2,783,926 to 2,787,948, reverse strand). Ensembl gene ENSG00000103355.
Subcellular location: Secreted
Gene Ontology:
Molecular function: serine-type endopeptidase activity; serine-type peptidase activity
Biological process: proteolysis
Cellular component: cytoplasm; extracellular region
Genetic constraint (gnomAD): Loss-of-function variants: 32 observed, 23.86 expected, observed/expected ratio (o/e) 1.34, 90% interval 1.01 to 1.78. The synonymous counts are far from expectation, so gnomAD's model fits this gene poorly and the ratio says little. Missense variants: 450 observed, 327.83 expected, observed/expected ratio (o/e) 1.37, 90% interval 1.27 to 1.48. Synonymous variants: 192 observed, 137.42 expected, observed/expected ratio (o/e) 1.4, 90% interval 1.24 to 1.58.
Homologues: Orthologues: macaque PRSS33 (90% identical), pig PRSS33 (82% identical), dog PRSS33 (80% identical), rabbit PRSS33 (80% identical), mouse Prss33 (80% identical), rat Prss33 (79% identical), guinea pig PRSS33 (78% identical), zebrafish zgc:100868 (40% identical), zebrafish si:ch73-182e20.3 (34% identical), zebrafish si:dkeyp-93a5.3 (34% identical), zebrafish si:ch73-182e20.4 (34% identical), zebrafish zgc:123217 (33% identical). Paralogues in human: PRSS27 (47% identical), PLG (37% identical), PRSS48 (37% identical), PLAT (34% identical), OVCH1 (32% identical), KLK15 (32% identical), PRSS50 (32% identical), KLK9 (32% identical), GZMM (31% identical), TMPRSS12 (30% identical), PRSS57 (28% identical), PRSS37 (24% identical), and 2 more.
Diseases named in the same sentence as PRSS33 in open-access papers:
PRSS33 is named in the same sentence as 10 diseases in open-access papers, as found by Europe PMC text mining. Sharing a sentence is not in itself a finding about the gene and the disease. The quoted sentences say what the papers report.
asthma (1 paper, 2020). "In accordance, we found the eosinophil marker genes RNASE2 (ribonuclease A family member 2), RNASE3, SIGLEC8 (sialic acid binding Ig-like lectin 8) and IL5RA as well as PRSS33 (serine protease 33) being exclusively expressed in eosinophils in the deconvolved asthma data." (PMID 33076907, 2020).
colon tumor (1 paper, 2022). "A subcluster of genes encoding proteases (PRSS33), protease inhibitors (R3HDML), and cytoskeletal factors (TNNC2) was overexpressed only in colon tumor tissues and resembled the expression pattern of LY6G6D." (PMID 35953834, 2022).
endometrial cancer (1 paper, 2024). Primary or metastatic malignant neoplasm involving the endometrium (mucous membrane that lines the endometrial cavity). "For instance, microbial analysis of endometrium from patients with endometrial cancer and healthy volunteers revealed that Prevotella and Pelomonas were enriched in the endometrial cancer group, Prevotella was significantly associated with three genes (PRSS33, CPB2, XBP1)." (PMID 39360320, 2024).
endometrial tumor (1 paper, 2021). "In our study, the expression of PRSS33 was significantly increased in endometrial tumor tissues, suggesting the functional effect of this protein on fibrin degradation." (PMID 34621695, 2021). "Multiplex immunofluorescence confirmed that PRSS33, CPB2 and XBP1 proteins were significantly highly expressed in the endometrial tumor tissues of patients with elevated DD and FDPs, suggesting that Prevotella could partially promote DD and FDPs by influencing host gene expression." (PMID 34621695, 2021).
Sepsis (1 paper, 2023). Sepsis is defined as life-threatening organ dysfunction caused by a dysregulated host response to infection. "Innate immunity and inflammation, such as ZDHCC19, ALOX15, FCER1A, HDC, PRSS33, and PCSK9, were upregulated in elderly ICU patients with sepsis." (PMID 36823620, 2023). "On day-8 in elderly ICU patients with sepsis, genes related to innate immunity and inflammation, such as ZDHCC19, ALOX15, FCER1A, HDC, PRSS33, and PCSK9, were upregulated." (PMID 36823620, 2023).
cancer (2 papers, 2021 to 2025). A tumor composed of atypical neoplastic, often pleomorphic cells that invade other tissues. "Despite these mechanistic insights, our study is the first to implicate LILRA6, CACNG6, and PRSS33 in cancer-related symptoms." (PMID 40577278, 2025). "Furthermore, the involvement of PRSS33 in amplifying inflammatory responses implies a potential correlation with cancer-related pain." (PMID 40577278, 2025). "In contrast, the roles of the serine proteases PRSS33 and PRSS53 have been less investigated in cancer progression, but there are indications that PRSS33 may play a role in tumor cell invasion." (PMID 34149812, 2021). "While the role of PRSS33 in pain has not been previously reported, it is noteworthy that proteases can activate receptor 2 (PAR2) signaling, a mechanism that may exacerbate cancer pain." (PMID 40577278, 2025).
infection (1 paper, 2025). The state of being infected such as from the introduction of a foreign agent such as serum, vaccine, antigenic substance or organism. "Many of the selected genes were immune‐related and play a role in the host response against infection, such as BPI, PRSS33, S100A9, CLEC4E, and so on." (PMID 39692191, 2025).
PRSS33 also shares sentences with these, for which no sentence is quoted: tumor (2 papers); colon carcinoma (1); psoriasis (1).